ZNF449 (zinc finger protein 449)
Description:
May be involved in transcriptional regulation.
Synonyms: ZSCAN19; FLJ23614
Tractability: PROTAC: ubiquitination databases record sites on it.
Gene: Protein-coding gene on chromosome X (135,344,199 to 135,363,413, forward strand). Ensembl gene ENSG00000173275.
Subcellular location: Nucleus
Subcellular location (Human Protein Atlas): Cytosol; Nucleoplasm
Gene Ontology:
Molecular function: protein binding; sequence-specific double-stranded DNA binding; DNA-binding transcription factor activity, RNA polymerase II-specific; RNA polymerase II cis-regulatory region sequence-specific DNA binding
Biological process: regulation of transcription by RNA polymerase II
Cellular component: nucleus
Homologues: Orthologues: chimpanzee ZNF449 (99% identical), macaque ZNF449 (99% identical), rabbit ZNF449 (92% identical), guinea pig ZNF449 (92% identical), dog ZNF449 (91% identical), rat Zfp449 (90% identical), mouse Zfp449 (90% identical), pig ZNF449 (90% identical). Paralogues in human: ZKSCAN8 (38% identical), ZSCAN12 (38% identical), ZSCAN30 (37% identical), ZKSCAN4 (36% identical), ZSCAN21 (36% identical), ZKSCAN3 (36% identical), ZNF394 (36% identical), ZKSCAN1 (35% identical), ZNF397 (34% identical), ZNF263 (34% identical), ZSCAN26 (34% identical), ZSCAN22 (33% identical), and 18 more.
Diseases named in the same sentence as ZNF449 in open-access papers:
ZNF449 is named in the same sentence as 1 disease in open-access papers, as found by Europe PMC text mining. Sharing a sentence is not in itself a finding about the gene and the disease. The quoted sentences say what the papers report.
cancer (1 paper, 2024). A tumor composed of atypical neoplastic, often pleomorphic cells that invade other tissues. "There are no reports of sex or survival specificity of ZNF449 in RCC or other cancers." (PMID 38982123, 2024).